ACER1 (alkaline ceramidase 1)
Description:
Endoplasmic reticulum ceramidase that catalyzes the hydrolysis of ceramides into sphingosine and free fatty acids at alkaline pH. Ceramides, sphingosine, and its phosphorylated form sphingosine-1-phosphate are bioactive lipids that mediate cellular signaling pathways regulating several biological processes including cell proliferation, apoptosis and differentiation. Exhibits a strong substrate specificity towards the natural stereoisomer of ceramides with D-erythro-sphingosine as a backbone and has a higher activity towards very long-chain unsaturated fatty acids like the C24:1-ceramide. May also hydrolyze dihydroceramides to produce dihydrosphingosine. ACER1 is a skin-specific ceramidase that regulates the levels of ceramides, sphingosine and sphingosine-1-phosphate in the epidermis, mediates the calcium-induced differentiation of epidermal keratinocytes and more generally plays an important role in skin homeostasis.
Synonyms: ASAH3; ALKCDase1
Tractability: Antibody: UniProt predicts a signal peptide or a membrane-spanning region.
Target class: Enzyme; Hydrolase
Gene: Protein-coding gene on chromosome 19 (6,306,142 to 6,333,612, reverse strand). Ensembl gene ENSG00000167769.
Subcellular location: Endoplasmic reticulum membrane
Pathways (Reactome):
Metabolism: Sphingolipid catabolism
Gene Ontology:
Molecular function: N-acylsphingosine amidohydrolase activity; protein binding
Biological process: cell differentiation; cellular response to calcium ion; ceramide catabolic process; epidermis development; keratinocyte differentiation; response to alkaline pH; sphingolipid biosynthetic process; sphingosine biosynthetic process; sphingolipid catabolic process; sphingolipid metabolic process; ceramide metabolic process; sebaceous gland development
Cellular component: endoplasmic reticulum; endoplasmic reticulum membrane; membrane
Genetic constraint (gnomAD): Loss-of-function variants: 31 observed, 29.66 expected, observed/expected ratio (o/e) 1.05, 90% interval 0.78 to 1.41. The upper end of that interval is the gene's LOEUF score, 1.41, which puts it in group 5 of 6, group 1 being the genes least tolerant of losing a copy. Missense variants: 352 observed, 357.68 expected, observed/expected ratio (o/e) 0.98, 90% interval 0.9 to 1.08. Synonymous variants: 132 observed, 134.03 expected, observed/expected ratio (o/e) 0.98, 90% interval 0.85 to 1.14.
Homologues: Orthologues: chimpanzee ACER1 (98% identical), macaque ACER1 (96% identical), dog ACER1 (85% identical), pig ACER1 (84% identical), mouse Acer1 (80% identical), guinea pig ACER1 (74% identical), rabbit ACER1 (71% identical), rat Acer1 (70% identical), tropical clawed frog acer1 (58% identical), zebrafish acer1 (49% identical), Caenorhabditis elegans W02F12.2 (28% identical). Paralogues in human: ACER2 (38% identical), ACER3 (20% identical).
Diseases named in the same sentence as ACER1 in open-access papers:
ACER1 is named in the same sentence as 13 diseases in open-access papers, as found by Europe PMC text mining. Sharing a sentence is not in itself a finding about the gene and the disease. The quoted sentences say what the papers report.
melanoma (3 papers, 2022 to 2025). A malignant, usually aggressive tumor composed of atypical, neoplastic melanocytes. "It would be interesting to investigate whether ACER1 has a protective function in melanoma development." (PMID 35565311, 2022). "It is particularly important to investigate the specific functions of ACER1 in melanoma (i.e., skin cancer), since ACER1 is crucial for keratinocyte differentiation, and there is already a known existing crosstalk between melanocytes, keratinocytes, and melanoma." (PMID 35565311, 2022). "The enrichment of these categories reflects the dysregulation of transcriptional programs typical of keratinocytes (e.g., SPRR1/2/3, KRT10/KRT16, LOR, IVL, EVPL, SCEL, TGM1/TGM3, CERS3, ACER1, DSP) and, above all, the epithelial crosstalk that influences melanoma biology." (PMID 41465101, 2025).
Farber disease (2 papers, 2020 to 2025). "A variety of alkaline ceramidases (ACER1-3) were associated with Farber’s disease and involved in the regulation of cell viability in the small intestine and colon cancer, yet these activities were not recorded in treatment with cedrol." (PMID 33585438, 2020).
inflammatory bowel disease (2 papers, 2024 to 2025). A spectrum of small and large bowel inflammatory diseases of unknown etiology. "Transcriptomic analysis revealed that alkaline ceramidase 1 (ACER1), an enzyme that regulates the levels of ceramides, is a promising therapeutic target for inflammatory bowel diseases associated with SLC39A8." (PMID 40933952, 2025).
alopecia (1 paper, 2016). Hair loss usually from the scalp. "Acer1‐deficient (Acer1−/−) mice showed elevated levels of ceramide in the skin, aberrant hair shaft cuticle formation and cyclic alopecia." (PMID 27126290, 2016). "The alopecia‐like phenotype and the obvious hair shaft cuticular abnormalities indicate that Acer1 is indispensable for the formation of the hair shaft cuticle and thus for maintaining hair function." (PMID 27126290, 2016).
colitis (1 paper, 2024). Inflammation of the colon. "In addition to the findings for Slc39a8-IEC KO intestines, our data demonstrate that dietary Mn deficiency upregulates Acer1 expression in the intestine and that treatment with an Acer1 inhibitor mitigates colitis in Mn-deficient mice." (PMID 38839750, 2024). "We further demonstrated that treatment with an ACER1 inhibitor significantly mitigated colitis in both preventive and therapeutic settings by enhancing the expression of tight junction proteins and inhibiting inflammation." (PMID 38839750, 2024). "We therefore examined the physiological relevance of ACER1 inhibition in the DSS-induced colitis model." (PMID 38839750, 2024). "Importantly, treatment with an ACER1 inhibitor attenuates colitis in Slc39a8-IEC KO mice by remedying barrier dysfunction." (PMID 38839750, 2024). "We also tested the protective effects of the Acer1 inhibitor on DSS-induced colitis in WT mice." (PMID 38839750, 2024). "Therefore, ACER1 is a key enzyme in sphingolipid metabolism, a process that is involved in mouse models of colitis and human IBD41–43." (PMID 38839750, 2024).
glioma (1 paper, 2023). A benign or malignant brain and spinal cord tumor that arises from glial cells (astrocytes, oligodendrocytes, ependymal cells). "When we assessed the expression of available ceramidases (ACER1 was unavailable) in primary and recurrent gliomas using the Chinese Glioma Genome Atlas (CGGA), we found that only ASAH1 was increased in recurrent gliomas while the other ceramidases were unchanged." (PMID 38086808, 2023).
Hypertension (1 paper, 2011). The presence of chronic increased pressure in the systemic arterial system. "In a case-control design using these definitions of hypertension the maximal single-gene heritabilities did not exceed 0.0034 and were all represented by the same three SNPs in ACER1, ACER2, and CERKa." (PMID 21569466, 2011).
Obesity (1 paper, 2020). Accumulation of substantial excess body fat. "The hypermetabolic 2 SD and 3 SD effects of Fgfr4+/-, Fgfr4-/-, and Acer1-/- contribute to resistance to obesity, while the effects of Pparg heterozygosity are modest at just over 1 SD." (PMID 32356724, 2020).
cancer (1 paper, 2022). A tumor composed of atypical neoplastic, often pleomorphic cells that invade other tissues. "Meanwhile, given the low expression of ACER1, TCGA data combining patients with these four different cancer types altogether had worse prognostic outcome." (PMID 35565311, 2022). "The role of ACER1 in cancer has not been elucidated and, therefore, ACER1-specific functions in cancer progression and survival are currently unknown." (PMID 35565311, 2022).
tumour (1 paper, 2025). "Genes such as ACER1, ASAH1 and SMPD1 exhibit significant differences in expression between tumour and normal tissues." (PMID 40159631, 2025).
ACER1 also shares sentences with these, for which no sentence is quoted: colon cancer (1 paper); dermatitis (1); skin cancer (1).